HDAC6 (histone deacetylase 6)
Diseases named in the same sentence as HDAC6 in open-access papers (continued):
Sharing a sentence is not in itself a finding about the gene and the disease.
infection (continued). "The observation that in IAV-infected cells the C terminus of HDAC6 (encompassing the ZnF domain) gets cleaved off by Caspase-3 at late stages of the infection may help to solve this conundrum." (PMID 34359892, 2021). "Our results suggested that HDAC6 may be a crucial player in mediating the degradation of ubiquitinated cGAS during diverse viruses’ infection, which needs to be explored in future." (PMID 34543359, 2021). "However, deletion of the UBA domain of p62 or the UBD of HDAC6 led to inhibition of the interaction between them even in the presence of CA16 infection." (PMID 32082291, 2020). "Therefore, HDAC6 inhibition assays, αTAT1 knock out cell infections, in situ cell fractionation, and confocal and TIRF microscopy were used." (PMID 32085463, 2020). "HDAC6 immunoprecipitated with p62 in the presence of CA16 infection." (PMID 32082291, 2020). "However, when viral particles are obtained in the presence of functional Nef, HDAC6 is degraded (either the endogenous or the over-expressed enzyme) and Vif is stabilized, assuring virion production with restored infection capacities." (PMID 31736889, 2019). "Hence, Δnef-virions lose their infection capacity when viral particles are produced in the presence of over-expressed HDAC6." (PMID 31736889, 2019). "Therefore, all these data prompted us to suggest that HDAC6 targets Pr55Gag and Vif, limiting viral production and infection, antiviral functions that are only entirely neutralized by full-length functional Nef (summary illustrations)." (PMID 31736889, 2019). "For example, HIV-1 fusion and infection are inhibited by HDAC6-mediated deacetylation of α-tubulin." (PMID 30518648, 2019). "Interestingly, we observed that virions produced with the Nef-EA mutant, despite being able to target HDAC6, present a low infection capacity." (PMID 31736889, 2019). "We observed that HIV-1 early infection was impaired when wt-HDAC6 was overexpressed in packaging HEK 293T cells, thus corresponding to conditions where Vif was degraded and A3G subsequently protected (histograms, compare control bar in lane 2 with lanes 3 and 4)." (PMID 26105074, 2015). "The related histone deacetylases, HDAC2 and HDAC6, failed to associate with viral DNA after infection." (PMID 20846395, 2010). "Importantly, the interaction between HDAC6 and TRIM56 was significantly upregulated at 4 h p.i., suggesting that HSV-1 early infection promotes the nuclear-to-cytoplasmic transport of HDAC6 and enhances its interaction with TRIM56, thereby reducing TRIM56-mediated cGAS-STING activation." (PMID 39747662, 2025). "Moreover, several studies that have characterized the functionality of the HIV-1 Env complex isolated from viruses of patients with extreme clinical phenotypes shed light on the events that occur in early infection, where HDAC6 plays an important role acting as a tubulin-deacetylase enzyme." (PMID 37685911, 2023). "Likewise, HDAC6 inhibits viral entry and infection, precisely impeding pore fusion formation." (PMID 37685911, 2023). "The TDP-43/HDAC6 axis could be another factor that is worth exploring as well as the immune responses in EC individuals that lose their status of natural controllers of the infection." (PMID 35682862, 2022). "Indeed, as we guessed that PCV2 did inhibit type I interferon expression via suppressing cGAMP production by gC1qR-mediated catalytic activity inhibition in the early phase of infection, and gC1qR/HDAC6/autophagy regulator axis-mediated cGAS degradation in the late phase of infection." (PMID 34543359, 2021). "HDAC6 may participate in the late phase of infection in various ways." (PMID 32085463, 2020). "Indeed, almost no SG-associated poly-Ub was detected in HDAC6 UBD deletion-transfected cells in the presence of CA16 infection." (PMID 32082291, 2020).
infection (continued). "Moreover, and instead with HDAC6 over-expression conditions, nascent virions obtained in the presence of functional Nef present enhanced infection capacities compared to Δnef-virions, which are poorly produced in the presence of HDAC6, as occurred with Nef mutants unable to target HDAC6." (PMID 31736889, 2019). "Similarly, specific inhibition of HDAC6 by tubacin increased infection of CD4 + T cells by HIV-1." (PMID 31744547, 2019). "To further investigate HDAC6’s role, we overexpressed HDAC6 in HEK293T cells and observed enhanced VSV infection." (PMID 41135681, 2025). "Next, we analyzed the effect of the TDP-43-mediated HDAC6 protein increase on HIV-1 viral production and the infection capacity of released viral particles." (PMID 37108826, 2023). "By targeting the HIV proteins Pr55Gag and viral infectivity factor (Vif), HDAC6 functions as an anti-HIV-1 limiting factor, reducing viral proliferation and infection." (PMID 37638049, 2023). "We previously reported that HDAC6 regulates HIV-1 viral production and infection by degrading Pr55Gag and Vif viral proteins by autophagy." (PMID 37108826, 2023). "In this sense, the tubulin-deacetylase HDAC6 appears to be crucial in the control of HIV-1 production and the infection capacity of nascent viral particles." (PMID 37685911, 2023). "In target cells where endogenous TDP-43 was silenced by using specific siRNA oligos, a significant decrease in the levels of HDAC6 occurred which favors HIV-1 Env-mediated fusion and infection." (PMID 35682862, 2022). "Altogether, these results prompted the suggestion that TDP-43 by conditioning HDAC6 mRNA and subsequent protein levels alters the permissive status of target cells against HIV-1 fusion and infection." (PMID 35682862, 2022). "It means that the level of expression of HDAC6 and the acetylation status/level of MTs determine the capacity of HIV-1-Env to promote membrane fusion (pore fusion formation), entry and infection." (PMID 35682862, 2022). "It has been reported that the level of expression of tubulin-deacetylase HDAC6 in target cells conditions HIV-1 Env-mediated pore fusion formation and early infection activities." (PMID 35682862, 2022). "The level of HDAC6 therefore conditions the amount of acetylated MTs that regulate HIV-1 Env-mediated pore fusion formation and infection." (PMID 35682862, 2022). "Other studies demonstrate that specific siRNA inhibition of HDAC6 increases HIV-1 entry due to the increased amount of acetylated α-tubulin that favors virus-cell membrane fusion (i.e., pore fusion formation) and infection." (PMID 33995324, 2021). "Taking together all the data, it is plausible to propose that HDAC6 is an anti-HIV-1 restriction factor, limiting viral production and infection, acting in the late steps of the viral cycle." (PMID 31736889, 2019). "The HDAC6 gene, involved in the HDAC6/STAT3/IL10 axis, was downregulated ~3-fold later on (24 hpi) during infection in JD(–) macrophages." (PMID 31969876, 2019). "Early after infection, TNFα, IL-1β, IL-6, IL12p70 and IFN-β levels were lower in supernatants from Hdac6-/- cells than in those from Hdac6+/+ cells, and this difference held at 12 and 24 hpi." (PMID 29281743, 2017). "HDAC6 overexpression inhibited the acetylation of α-tubulin, and prevented HIV-1 envelope-dependent cell fusion and infection." (PMID 28052127, 2017). "Then, we quantified the effects of HDAC6-mediated proviral Vif degradation on early HIV-1 entry and infection by using a pNL4.3.LucR-E- provirus (bearing the lacZ gene)." (PMID 26105074, 2015). "Expression of several histone deacetylases was also regulated during infection: HDAC2 and HDAC10 expression levels increased, while HDAC3, HDAC6, and HDAC9 expression decreased." (PMID 18331636, 2008).
infection (continued). "PRV and VSV infection in HDAC6-KO cells increased acetyl-H2AX by approximately 43% and 13%, respectively, whereas PRV and VSV infection in HDAC6-overexpressing cells decreased acetyl-H2AX by approximately 33% and 22%, respectively, compared to infection in NT cells." (PMID 39861880, 2025). "Finally, we discovered that the viral protein US3 phosphorylates cytoplasmic HDAC6 to increase its deacetylase activity and interaction with TRIM56 in the early infection stage." (PMID 39747662, 2025). "In addition, a fluorometric kit was employed to assess the deacetylase activity of HDAC6, which showed a reduced AFC fluorescence intensity by HSV-1 early infection, whereas tubacin notably upregulated AFC fluorescence intensity." (PMID 39747662, 2025). "In this respect, the ubiquitin-binding activity, but not the deacetylase activity, of HDAC6 is required for efficient viral uncoating and infection." (PMID 39861880, 2025). "HDAC6-mediated deacetylation of α-tubulin, for example, inhibits HIV-1 fusion and infection." (PMID 37638049, 2023). "Altogether, these data indicate a new function for TDP-43 and the TDP-43/HDAC6 axis in modulating HIV-1 viral production and virion infection efficiency through the stabilization of HDAC6 and the promotion of the autophagic degradation of HIV-1 Vif and Pr55Gag proteins." (PMID 37108826, 2023). "Here, P. gingivalis lowered the levels of α-tubulin acetylation during infection and oxidative stress, which was independent of the increased expression of HDAC6, the major α-tubulin deacetylase." (PMID 36985180, 2023). "Then, HDAC6 stabilization by the overexpression of wt-TDP-43 generates a non-permissive state for target cells by impairing MT stabilization and making HIV-1 Env/CD4-mediated pore fusion formation and subsequent viral entry and infection difficult." (PMID 37108826, 2023). "HDAC6 impairs HIV-1-mediated stabilization of a cortex of stable and acetylated MTs in their α-tubulin subunits, which is required for efficient viral entry and infection, and is directly dependent on the first viral Env/CD4 interaction and signaling." (PMID 35682862, 2022). "The authors propose that due to the importance of HDAC6 for limiting HIV-1 fusion and infection in the first step of the viral cycle, TDP-43 conditions cell permissivity to fuse and become infected by HIV-1 by regulating HDAC6 expression at mRNA and protein levels." (PMID 35682862, 2022). "Moreover, HDAC6 inhibition increased the release of pro-inflammatory cytokines (TNF and IL-12) upon infection with other bacteria, e.g. Mycobacterium tuberculosis." (PMID 36131943, 2022). "On the contrary, over-expression of HDAC6, which is located in the cytoplasm and regulates deacetylation of α-tubulin in stable microtubules, inhibits HIV-1 Env-mediated tubulin acetylation, thereby preventing HIV-1 Env-dependent cell fusion and infection." (PMID 33995324, 2021). "There is no canonical SGs in HDAC6 knockdown cells with the treatment of poly I:C or CA16 infection." (PMID 32082291, 2020). "Another potential therapeutic target for CF was proposed to be histone deacetylase 6 (HDAC6), as its depletion, in a mouse model, reduced the recruitment of neutrophils to the lungs, followed by an improved response to infection and an increased rate of bacterial clearance and reduced weight loss." (PMID 32367193, 2020). "Histone deacetylase 6 (HDAC6) plays both enzymatic and scaffold roles in diverse cellular processes including autophagy, pathogen sensing, and cellular cargo movement, related to infection and innate immunity." (PMID 31432234, 2019). "In this regard, our results suggest that Nef-PPAA poorly interacts with and does not target HDAC6, thereby being unable to prevent HDAC6 restrictions for viral production and infection, acting on Pr55Gag and Vif." (PMID 31736889, 2019). "In this context, we aim to seek for a potential interplay between HDAC6 and Nef, which could be key in the control of HIV-1 viral production and infection." (PMID 31736889, 2019).
infection (continued). "Therefore, it is plausible to consider HDAC6 as an anti-HIV restriction factor neutralized by Nef to foster a favorable environment for viral production and infection." (PMID 31736889, 2019). "The anti-Vif activity is mediated by the HDAC6-proautophagy function, thus impairing HIV-1 infectiveness as we reported, and correlates with a less infectious cell-supernatant, as further measured in early infection experiments in permissive T-cells (lane 4)." (PMID 31736889, 2019). "Consequently, our results suggest that HDAC6 acts as an anti-HIV-1 restriction factor, limiting viral production and infection by targeting Pr55Gag and Vif." (PMID 31736889, 2019). "The absence of this effect during BMDC in vitro infection by the non-intracellular bacteria S. aureus and E. coli DH5α indicates that Hdac6-/- BMDCs are specifically unable to efficiently clear intracellular pathogens." (PMID 29281743, 2017). "On the other hand, HDAC6-mediated microtubule deacetylation impairs the IVA cycle, preventing trafficking of viral components to the viral assembly site in the host plasma membrane and the spread of infection to surrounding cells." (PMID 29281743, 2017). "Moreover, aggrephagy factors including Parkin, HDAC6, and HSP25/27 were all required for efficient infection-induced autophagy and recruitment of LC3 to chlamydial structures." (PMID 28634388, 2017). "During infection with Influenza Virus A (IVA), HDAC6 appears to play a dual role." (PMID 29281743, 2017). "Lack of HDAC6 also decreased the relative mRNA levels of the pro-inflammatory cytokines TNFα, IL-1β and IL12p40, indicating impaired cytokine activation after infection." (PMID 29281743, 2017). "Velenzuela-Fernandez and colleagues also report that HDAC6 knockdown increased HIV infectivity and syncytia formation, while over-expression of HDAC6 impaired HIV-1 envelope-dependent infection and cell fusion, yet left the HIV receptor expression and co-distribution unaltered." (PMID 24832229, 2012). "With the identification of the interaction between the M protein of CoVs and HDAC6, it is plausible that CoVs not only regulate ciliary disassembly but also leverage HDAC6 to facilitate rapid transport from the MTOC to target organelles along the microtubule following infection and membrane fusion." (PMID 40938964, 2025). "The nuclear localization signal (NLS)-TDP-43 mutant was not able to control the HIV-1 viral production and infection and could not stabilize HDAC6, as previously reported in CD4+ T permissive cells." (PMID 37108826, 2023). "In addition, the Valenzuela–Fernández group have found that the silencing of TDP-43 was able to reduce the expression of the antiviral enzyme histone deacetylase 6 (HDAC6), both at the mRNA and protein level, increasing the fusogenic and infection activities of HIV-1." (PMID 36675095, 2023). "Moreover, HDAC6 inhibitors could also flank CFTR-targetedtherapies in order to improve the management of inflammation, fibrosisand infection in CF." (PMID 35148101, 2022). "However, other authors have reported opposite observations using pan-HDAC inhibitors or specific inhibitors of HDAC6 during infection of human macrophages with the Gram-negative intracellular pathogens S. Typhimurium and E. coli." (PMID 29281743, 2017). "The prospect that multiple key CF phenotypes can be addressed by HDAC6 inhibition is important for patients with CFTR mutations not currently responsive to potentiator and corrector therapies, or to even augment CFTR-targeted therapies to improve inflammation and infection management." (PMID 31311988, 2019). "High TDP-43 levels, on the other hand, change the cellular level of the HDAC6 antiviral factor, preventing HIV-1 envelope complex (Env) fusion and infection regardless of viral Env tropism and strain." (PMID 37638049, 2023).
infection (continued). "This means that functional HIV-1 Envs with the ability to vault the HDAC6 barrier establish a productive infection, while HIV-1 Envs from viruses that have lost this ability do not set a correct signal and infection, as occurs with viral Envs isolated from viruses of EC individuals." (PMID 37108826, 2023). "Although our work has shown the positive regulation of HDAC6 expression level on viral infectivity, this finding may not be consistent for viruses other than PRV and VSV, as some viruses are type I IFN insensitive or have an inhibitory effect on type I IFN response during infection." (PMID 39861880, 2025).